CD4 (CD4 molecule)
Diseases named in the same sentence as CD4 in open-access papers (continued):
Sharing a sentence is not in itself a finding about the gene and the disease.
tumor (continued). "Additionally to the generally increased infiltration of monocytes/macrophages and T cells in those tumors, higher concentrations of monocytes/macrophages and the γδ, NKT and CD4+ T cell subsets correlated with good abscopal responses (lower tumor weight) in those tumors." (PMID 33572437, 2021). "However, CD4+ T-cell subtypes in the TME have varying impacts on tumor behavior." (PMID 34944826, 2021). "Previously, we developed a syngeneic orthotopic mouse GBM-model of tumor resection and showed that tumor debulking results in a substantial reduction in myeloid-derived suppressor cells (MDSCs) and simultaneous recruitment of CD4/CD8 T cells into the resection bed." (PMID 33668856, 2021). "Notably, adoptive transfer of activin-A-treated CD4+ T cells (act-A-CD4+ T cells) into tumor-bearing CD4−/− mice led to restrained lung tumor formation in comparison to mice transferred with PBS-treated CD4+ T cells (PBS-CD4+ T cells) or mock-transferred CD4−/− mice (no cells)." (PMID 34548096, 2021). "During transition from naïve CD4+ T cells, Tregs switch from Glc utilization to other fuel sources such as fatty acids, which could help sustain their function in low Glc conditions such as in the tumor microenvironment." (PMID 34709178, 2021). "Hence molecules secreted by tumor cells and CAFs could shape the future of the CD4+ T cells enrolled into the TME into Tregs and Th17 cells." (PMID 33996630, 2021). "For example, macrophages are generally dichotomized into M1 inflammatory/anti-tumor and M2 pro-tumoral/pro-angiogenic macrophages, and CD4 T cells can be Th1, Th2, Th17, T regulatory cells, or other newly identified CD4 T cell subsets that may have either pro- or anti-tumor characteristics." (PMID 34359840, 2021). "Furthermore, the heatmap analysis of immune cell infiltration by transcriptomic data showed that immune effector cells were significantly accumulated in recurrent tumor including activated CD4+ T cells, activated CD8+ T cells, natural killer cells, and immature dendritic cells." (PMID 34903219, 2021). "However some subsets of CD4+ cells can exhibit pro-tumor functions." (PMID 33842331, 2021). "Notably, a tumor stage-dependent increase in CD4+ TEM cells was observed." (PMID 34868015, 2021). "In addition, we found that key immune-checkpoint inhibitors and their ligands such as PD1-PDL1 (CD274) and CTLA4-CD80/86 had higher interaction score in tumor than that in normal samples, in concordant with our above observation that both CD4 and CD8 T cells were more exhaustive in tumor samples." (PMID 34921160, 2021). "High levels of CD8+ cytotoxic T lymphocytes and CD4+ helper T cells are in general favorable prognostic indicators whereas other immune cells, such as regulatory T cells and tumor-associated macrophages (TAM)s, may promote tumor progression." (PMID 34209309, 2021). "Recent data have demonstrated an upregulation of the tumor-immune system in subjects undergoing chemotherapy by activating CD8+ (Th1) TILs, positively correlating with improved responses and even with increased survival Similarly, higher CD4-TILs (Th2) have been associated with favorable outcomes." (PMID 34944876, 2021). "Treg cells are usually identified as a specialized subset of CD4+ T cells functioning in the establishment and maintenance of immunosuppression, such as promoting the resolution of inflammation, suppressing aberrant immune responses against self-antigens, and limiting anti-tumor immune responses." (PMID 34248142, 2021). "The expression of the IL-2 Rα subunit on CD4+ regulatory T cells (Tregs) results in the preferential stimulation of these immunosuppressive cell types and is reported to limit the stimulatory effects of IL-2 on effector populations needed for anti-tumor responses." (PMID 34373459, 2021).
tumor (continued). "Overall, CD4+ helper T cells play an equally important role as CD8+ effector T cells in cancer immunity, and the inhibition of TGFB signaling pathway in CD4+ T cells can effectively trigger a complete wound healing response, causing tumor cell death through cutting off nutritional support." (PMID 34145032, 2021). "However, tissue-specific conditions or differences in the tumor niche may skew the differentiation of CD4+ T cells towards other Th subsets." (PMID 33777008, 2021). "Additionally, high CD4+ T cell count in the tumor correlated with better outcome." (PMID 33562138, 2021). "However, future versions of this model may incorporate the assumption of CD4+ T cell’s direct cytotoxicity against tumor cells if further evidence becomes available." (PMID 34559809, 2021). "Additionally, CD4 Th1 subsets could orchestrate anti-cancer immunity and enhance the activation and development of tumor-specific CD8 T cells by producing IFN-γ, TNF-α, and interleukin-2." (PMID 33407498, 2021). "Sixty-two represents the highest number of tumor neoantigens targeted by a personalized cancer vaccine, and the vaccination induced in mice a potent T cell response in mice against a number of encoded neoantigens comprising antigen-specific IFN-γ secreting CD8+ and CD4+ T cells." (PMID 34452005, 2021). "Therefore, it seems that the presence of a high number of tumor cells in the LN may diminish CD4+ T cells." (PMID 32808188, 2021). "Moreover, CD4+ CD25+ FOXP3 regulatory T cells (TREG) is one of the most studied cell population in the study of tumor microenvironment, which displayed the immunosuppressive role and could be a target of immunotherapy in the HCC." (PMID 34527684, 2021). "Hence, the identification of factors that can direct persistent, effective CD4+ T cell-mediated anti-tumor responses may set the groundwork for future efficacious cancer immunotherapies." (PMID 34548096, 2021). "Consequently, the high density of CD4+Foxp3+ T-cells in the tumor immune microenvironment could represent a state of immune activation, which may be the reason for the correlation between the density of CD4+Foxp3+ T-cells and OS in this study." (PMID 34647108, 2021). "However, both the number of tumours per liver and tumour size were reduced, suggesting that depletion of CD4+ T cells or regulatory T cells might contribute to tumour control." (PMID 33762733, 2021). "To explore the change in the number of immune cells in tumor tissues, we further detected the number of CD4+ and CD8+ T cells in the spleens of mice, and found that the combination treatment group could also significantly increase the number of immune cells in the spleens." (PMID 34295341, 2021). "Notably, tumor-infiltrating CD4+/CD8+ T cells were significantly more than those in RT + αPD-L1 group (2.65%/0.91% in primary tumors, 2.64%/1.04% in distant tumors), indicating that H@Gd-NCPs mediated radiosensitization created a favorable immunological microenvironment for antitumor therapy." (PMID 33420008, 2021). "When the enhanced infiltration of CD4+ T cells in the bilateral tumor model was observed, we realized that Tregs (regulatory T cells, occupied 20~30% CD4+ T cells in tumor tissues) might play a role in hindering the immune response in the tumor microenvironment." (PMID 33420008, 2021). "Though we found ex vivo expanded CD4+ and CD8+ T cells derived from PBMCs or TILs capable of LAIR2 secretion, selective expression by tumor-associated Treg cells in situ suggests that the tumor microenvironment may have a role in regulating LAIR2 expression." (PMID 35008369, 2021). "Indeed, in our study, patients in the high-FHPS group were found to have a high hypoxia state, suggesting that the anti-tumor effect of significantly infiltrated CD4+ T cells may be limited due to hypoxia, which further promotes an immunosuppressive state." (PMID 34977159, 2021).
tumor (continued). "High S100P expression reduced the infiltration of macrophages and CD4 + T cells, thereby promoting tumor immune escape, and decreased the expression of common immune inhibitors, suggesting that S100P inhibition may improve the expression of treatment targets to improve the efficacy of immunotherapy." (PMID 34654352, 2021). "Since the tumor microenvironment was composed of a large number of immune cells, we then examined the association between MALT1 copy number and infiltration level of several immune cells in PCa, such as B cell, CD4+ T cell, CD8+ T cell, macrophage, neutrophil and dendritic cell (DC)." (PMID 34926571, 2021). "The different proportions of immune cells including B cells, cancer associated fibroblasts, CD4+ T cells, CD8+ T cells, endothelial cells, macrophages in normal, primary and matched liver metastasis tissues reflect the different immune microenvironment status across stages of tumor progression." (PMID 34453042, 2021). "Therefore, more work is being undertaken to identify target tumour epitopes for CD4 T cells." (PMID 34858415, 2021). "Although we found that CD8+ and CD4+ T cells accumulate more in the central areas of the tumor in the present study, whether Apelin-induced accumulation of immune cells is specific for these T cells or whether other cell types also accumulate is still not clear." (PMID 34234274, 2021). "The results showed that the UPR pathway may be associated with the infiltration of activated CD4 T cell, type 2 T helper cell, gamma delta T cell, CD56bright natural killer cell, activated dendritic cell and central memory CD8 T cell in tumour tissues (p < .001)." (PMID 34187252, 2021). "Moreover, the percentage of Treg (CD4+, CD25+, FoxP3+), which is associated with a poor prognosis, was not altered by KLS-3010, while effector T cells (Teff; CD8+ IFF-γ+, and CD4+ IFF-γ+) were significantly increased among tumor-infiltrating lymphocytes in KLS-3010-treated mice." (PMID 32854548, 2021). "Additionally, SKA2 expression exhibited a significantly positive association with the CD8 + T cells, macrophages, neutrophils infiltration, and tumor purity, and a negative association with CD4 + T and Dendritic cells infiltration (P < 0.05)." (PMID 34845974, 2021). "In addition, significantly more Man-MPs were enriched in M2-like TAMs compared with those in other cells, including GFP-positive tumor cells, M1-like TAMs, dendritic cells (DCs), CD4+ T cells, CD8+ T cells, MDSCs, and Tregs, suggesting the superior M2-like TAM-targeting capability of Man-MPs." (PMID 33469052, 2021). "Moreover, interferon-γ (IFN)-γ secreted by cells participating in tumour elimination (i.e. CD4+ T helper 1 cells and activated T cells) may induce high PD-L1 expression in tumour cells." (PMID 35047074, 2021). "Interestingly, the tumour-reactive cytotoxic CD4+ T cells were demonstrated to play a role in immunity against human cancers and several studies indicate that their activity may be enhanced by the ICP inhibitor treatment." (PMID 34298847, 2021). "Researches indicated that exosomes from either the in vitro culture of tumor cells or the peripheral blood of tumor-bearing patients could educate CD4+CD25- T cell into iTregs with elevated granzyme B level, which effectively suppressed the immune responses against tumors." (PMID 33868318, 2021). "Thus, activated CD4+ and CD8+ T cells and CD4+/CD8+ effector memory T cells may indicate tumor response and adverse events." (PMID 34360781, 2021). "Our findings provide evidence that GBM might be influencing the state of tumor infiltrating CD4+ T cells by epigenetic modification in the form of DNA methylation of key immune function regulating genes and influencing the fate of helper T cells in the GBM TME." (PMID 34012510, 2021).
tumor (continued). "Activated CD4 memory T cells were involved autoimmune processes, M1 macrophages functioned in proinflammatory, microbicidal, and tumor resistance processes, and resting dendritic cells induced tumor immune tolerance through the receipt of immunosuppression signals." (PMID 34026364, 2021). "CD4 + T cells recognize antigens presented by human leukocyte antigens (HLA) class II receptors, consistently, the Pt38 tumor cells express HLA class II proteins, suggesting that CD4 + T cells in Pt38 opT may directly recognize the antigens presented by tumor cells." (PMID 34789550, 2021). "Lymphocytes, including cytotoxic lymphocytes and CD4+ T helper cells reflect host immunity status and mediate the host immune response to cancer; furthermore, lymphocytes have antitumor effect via suppression of cancer cell proliferation and invasion and promotion of tumor cell apoptosis." (PMID 33718126, 2021). "In addition, six tumor-infiltrating immune cells, including naive B cells, regulatory T cells, memory resting CD4 T cells, memory B cells, activated mast cells, and resting NK cells, were significantly overexpressed in the low-TMB group relative to the high-TMB group." (PMID 33758620, 2021). "The immune cell population of T cells CD4 memory activated has higher cell content in the OS group, which might suggest that CD4+ T memory cells were activated and the number of these cells increased to participate in the destruction of OS tumor." (PMID 34922489, 2021). "Moreover, CD4+ T-cell memory induced by optimal signal 1 alone was significantly more protective against retroviral infection and tumor challenge than standard vaccines or immunization regimens, including natural infection and tumor challenge." (PMID 32313208, 2021). "Purified CD4+ T cells from a cohort of non-small-cell lung carcinoma (NSCLC) patients showed a Tfh signature associated with heightened CTL proliferation and adoptive transfer of Tfh cells in a murine tumor model augmented CTL function and inhibited tumor growth in vivo." (PMID 34012451, 2021). "Indeed, in different models, GSDME activation promotes tumor suppression by increasing the anticancer properties of tumor-infiltrating natural killer (NK) cells and CD4+ and CD8+ T lymphocytes, together with an antitumor vaccination effect, triggering both innate and adaptive antitumor immunity." (PMID 33467668, 2021). "Application of this protocol to human hepatocarcinoma for the isolation of specific tumor peptides from both MHC-I and MHC-II pathways allowed the creation of the first multi-epitope, multi-target, and multi-allele vaccine targeting activation of CD4+ and CD8+ T cells." (PMID 33499042, 2021). "In addition, this nanoparticle also triggered cell surface exposure of CALR, as well as an abscopal effect in tumor-bearing mice, which likely increased the efficacy of ICIs through a more important recruitment of CD4+ and CD8+ cytotoxic T-cell populations in the tumors." (PMID 34834202, 2021). "Thus, removal or reduction of the Treg cell population, or inhibition of CD4+CD25++Treg function in the HCC microenvironment may facilitate the efficacy of tumour immunotherapy." (PMID 33995362, 2021). "Despite the recent advances demonstrating the importance of the CD4+ T-cell response to tumor-specific mutations in the HLA-II context, we have not included HLA-II predictions in our models as they are much less reliable and have not begun full implementation in human trials as of yet." (PMID 35611186, 2021). "Moreover, MSCs injected 14 days after tumor induction induced the generation of an immunosuppressive phenotype in CD4+T lymphocytes and prevented the trans-differentiation of TGF-β and IL-10-producing Tregs into anti-tumorigenic IFN-γ- and IL-17-producing Th1 and Th17 cells." (PMID 34830312, 2021).
tumor (continued). "The expression levels of CD8A (encoding CD8, marker of CD8+ T cells), CD4 (encoding CD4, marker of CD4+ T cells), and CD3D (encoding CD3, marker of T cells) were also significantly high in the low-risk groups, indicating higher abundance of the tumor suppressor T-cell subpopulation." (PMID 34641822, 2021). "However, major limitations are the availability of autologous tumor cells as antigenic source and the selection of antigen that may have potential to activate both CD4+ and CD8+ T cells in immune-specific manner." (PMID 34493268, 2021). "Therefore, CD4+ T cells would be a major research direction of NHE family in tumor immunity." (PMID 34759967, 2021). "Tumor antigens that are recognized by CD4+ T cells can be non-mutated or mutated." (PMID 33546283, 2021). "When curcumin was orally administered before tumor development in combination with Listeria-Mage-b therapeutic vaccine, the production of IL-6 was significantly decreased, and IL-12 was increased by MDSCs in correlation with improved CD4+ T and CD8+ T cell responses in blood." (PMID 34948368, 2021). "Therefore, we have identified a new function of FXR, which exerts pivotal effect in the immune microenvironment, not only by regulating the level of PD-L1 in HCC cells but also by affecting tumor-derived Exos to regulate CD4+ T cell immune costimulatory targets." (PMID 34888230, 2021). "Furthermore, whether cDC1 cells utilize PSGL-1 during tumor antigen presentation to both CD4+ and CD8+ T cells is unknown." (PMID 33708224, 2021). "Interestingly, other studies have found that IL-21 may be responsible, in part, for the anti-tumor functions of helper CD4+ T cells." (PMID 33809259, 2021). "The incubation of tumor cells with splenic T cells derived from B16F10-bearing mice treated with the local CAER led to the activation of a greater number of tumor antigen-specific CD4+ T cells and CD8+ T cells than that with T cells in the other treatment groups." (PMID 33859948, 2021). "Although most cell therapies focus on CD8+ CTLs due to their tumor killing capabilities, considering the molecular ‘help’ by CD4+ TH cells is required for CD8+ cytotoxicity and recruitment, adoptive transfer of CD4+ T cells may play an important role in overall tumor immune response." (PMID 34012451, 2021). "HLA transgenic mice vaccinated with citrullinated vimentin and α-enolase peptides linked to an adjuvant (Modi-1 vaccine) can stimulate CD4+ T cells and generate potent anti-tumor responses resulting in tumor regression and eradication with no associated toxicity." (PMID 33859638, 2021). "This type of tumor was characterized by the stromal positivity for PD-L1 and the infiltration of FOXP3+CD4+ T cells, indicating the development of a potentially immunosuppressive stromal microenvironment and partially explaining the worse overall survival of the patients with this type of tumor." (PMID 34885122, 2021). "In humans, Hodgkin’s lymphoma (HL) has among the highest response rates to ICB therapy (greater than 70%), but HL cells frequently downregulate MHCI expression, which indicates that CD4+ T cells may play an important role in generating tumor immunity in these patients." (PMID 34283809, 2021). "Typical Sézary cells have a CD3+CD4+CD8- phenotype; however, in cases of the aberrant loss of antigens on Sézary cells, especially the loss of critically important T-cell antigens such as CD4, there is a possibility of misdiagnosing the disease or underestimating the tumor burden of the disease." (PMID 34123441, 2021). "Moreover, analysis of immune landscape suggested that the tumor microenvironment (TME) and tumor-infiltrating lymphocytes (macrophages M0, monocytes, NK cell activation, T cell CD4+ naive and Tregs) were significantly different between the high-risk group and low-risk group." (PMID 35118063, 2021).